PTX3 (pentraxin 3)
Diseases named in the same sentence as PTX3 in open-access papers (continued):
Sharing a sentence is not in itself a finding about the gene and the disease.
unstable angina pectoris (6 papers, 2012 to 2021). "Moreover, in a recent clinical study, suggesting that PTX3 concentrations may have been a good predictive diagnostic tool for unstable angina pectoris, plasma, PTX3 levels have been significantly increased in patients with unstable angina pectoris." (PMID 22966213, 2012). "Plasma PTX3 levels are elevated in patients with unstable angina pectoris and in patients undergoing coronary stenting." (PMID 34658887, 2021). "PTX3 expression, similar to that of CRP, is increased also in coronary plaques of patients with unstable angina pectoris (UAP) compared to those with stable angina (SAP)." (PMID 23690668, 2013).
allergic asthma (5 papers, 2012 to 2023). A asthma with a basis in a pathological type I hypersensitivity reaction. "Silencing Ptx3 significantly alleviated allergic inflammation in Mettl3 KO mice, whereas higher PTX3 expression in plasma was positively associated with airway inflammation in childhood allergic asthma." (PMID 37957139, 2023). "Taken together, our data suggest that PTX3 deficiency mediated increased inflammatory response in the context of allergic asthma is in part due to enhanced DCs function." (PMID 34305885, 2021). "Noticeably, our data also uncovered that plasma levels of PTX3 were higher in childhood allergic asthma patients, showing a positive correlation with disease severity." (PMID 37957139, 2023). "To further elucidate the potential importance of PTX3 in allergic asthma, we evaluated its expression in childhood allergic asthma and healthy controls." (PMID 37957139, 2023). "In line with observations in the mouse model, both the PTX3 mRNA levels in monocyte-derived macrophages and PTX3 circulating levels in plasma were higher in childhood allergic asthma than in healthy participants." (PMID 37957139, 2023). "A connection between PTX3 and type 2 immune responses was also established in an experimental model of ovalbumin‐induced allergic asthma in mice." (PMID 32246830, 2020). "In human patients, PTX3 levels in BALF and sputum significantly correlate with disease severity and have been associated with allergic asthma in adults and children." (PMID 32246830, 2020). "Previously we showed enhanced PTX3 expression in the lungs of subjects with severe allergic asthma compared to healthy donors." (PMID 31437159, 2019). "Considering an inflammatory milieu in allergic asthma, we then investigated the effect of proinflammatory, Th2, and Th1 cytokines on PTX3 protein release by HASMC." (PMID 22529962, 2012). "Taken together, our data suggest a potential dual role of PTX3 in allergic asthma by enhancing airway inflammation via local CC chemokine expression from HASMC; and down regulating the remodeling by counteracting FGF-induced HASMC migration." (PMID 22529962, 2012). "Importantly, large cohorts of childhood allergic asthma need to be constructed, which evaluate the possibility of METTL3 or PTX3 levels as potential biomarkers for the diagnosis and assessment of childhood allergic asthma." (PMID 37957139, 2023). "Taken together, these findings imply that PTX3 may be a potential biomarker for the diagnosis and assessment of childhood allergic asthma." (PMID 37957139, 2023). "Additionally, PTX3 circulating levels showed a positive correlation with blood eosinophils numbers and FeNO levels in childhood allergic asthma." (PMID 37957139, 2023). "Interestingly, we noted that PTX3 levels exhibited the inverse correlation with METTL3 in monocyte-derived macrophages from childhood allergic asthma patients." (PMID 37957139, 2023). "ROC curve analysis, yielding AUC values of 0.69, indicated that PTX3 circulating levels in plasma may be useful for diagnosing childhood allergic asthma." (PMID 37957139, 2023). "Moreover, patients with allergic asthma show significantly higher PTX3 expression in airway smooth muscle cells as compared to healthy donors." (PMID 32246830, 2020). "More recently, we demonstrated that PTX3 deficient mice exhibit enhanced inflammation, AHR and mucus production upon OVA sensitization and challenge strongly suggesting a protective role of PTX3 in a murine model of allergic asthma." (PMID 31437159, 2019). "Considering an ‘inflammatory-like’ phenotype of ASMC, we hypothesized that PTX3 may also be involved in airway diseases such as allergic asthma." (PMID 22529962, 2012). "The present study is the first description of PTX3 expression in patients with allergic asthma." (PMID 22529962, 2012).
allergic asthma (continued). "Considering HASMC as one of the major cell types in the airway, constitutive expression and inducible PTX3 produced from this source may play a dual role in inflammatory and airway remodelling process in allergic asthma." (PMID 22529962, 2012). "However, very little is known about the expression of PTX3 and its role in allergic asthma." (PMID 22529962, 2012). "A detailed, comprehensive investigation into how the PTX3/STX17 axis modulates autophagy and macrophage homeostasis in allergic asthma is certainly needed." (PMID 37957139, 2023). "We observed that Ptx3 deficiency markedly attenuated Mettl3 knockout-induced airway inflammation in allergic asthma by suppressing M2 macrophage activation, but the effect of PTX3 on the other cells in vivo can not be excluded." (PMID 37957139, 2023).
ankylosing spondylitis (5 papers, 2015 to 2024). An autoimmune chronic inflammatory disorder characterized by inflammation in the vertebral joints of the spine and sacroiliac joints. "Smurf2 regulates angiogenesis by promoting the ubiquitination and degradation of Pentraxin 3 (PTX3), highlighting the role of E3 ubiquitin ligases in the abnormal angiogenesis associated with ankylosing spondylitis pathology." (PMID 39211390, 2024). "Findings.(i) Serum amyloid P and pentraxin 3 levels were significantly higher in patients with ankylosing spondylitis compared to healthy controls." (PMID 35685583, 2022). "(ii) Serum amyloid P and pentraxin 3 may be useful markers for disease activity in ankylosing spondylitis patients with normal traditional acute phase reactant levels." (PMID 35685583, 2022).
carotid atherosclerosis (5 papers, 2014 to 2023). A thickening and loss of elasticity of the walls of carotid arteries that occur with formation of atherosclerotic plaques. "Moreover, pentraxin 3 (PTX3) is described as an independent risk factor for the occurrence and severity of carotid atherosclerosis, and its increased levels in blood and plaque are correlated with carotid plaque instability." (PMID 33153204, 2020). "Pentraxin 3 (PTX3), another acute phase protein, constitutes a potential inflammatory biomarker and is shown to be independently associated with the severity of carotid atherosclerosis." (PMID 34829489, 2021). "This suggests an association between carotid atherosclerosis and the local production of not only IL-6 but also E-selectin, VCAM-1 and PTX3." (PMID 24936646, 2014). "In subgroup comparisons, it was found that patients with progression of carotid atherosclerosis had a higher serum concentration of pentraxin 3 (11.4 pg/mL (6.70–13.9) versus 6.82 pg/mL (2.54–11.5) (p = 0.034)) and lower IFNγ (14.9 pg/mL (10.4–18.7) versus 20.8 pg/mL (14.8–25.3) (p = 0.008))." (PMID 37569579, 2023). "According to the results of univariate and multivariate Cox regression analysis, an increase in pentraxin 3 above certain cut-off values and a decrease in IFNγ below certain cut-off values did not significantly increase the RR of carotid atherosclerosis progression." (PMID 37569579, 2023).
Cerebral ischemia (5 papers, 2019 to 2023). Restriction of arterial blood supply to the brain associated with insufficient oxygenation to support the metabolic requirements of the tissue. "Accordingly, neurogenesis and angiogenesis were inhibited after cerebral ischemia in Ptx3 null mice, and neuronal damage was increased after limbic seizure when Ptx3 deficient animals were compared to controls." (PMID 36012705, 2022). "Another report showed that PTX3-deficient mice subjected to experimental cerebral ischemia showed reduced neurogenesis in the dentate gyrus of the hippocampus." (PMID 31354697, 2019). "Interestingly, mice deficient for PTX3 had marked increase in tissue damage and unresolved cerebral edema after 6 days of cerebral ischemia." (PMID 31354697, 2019). "The findings that PTX3 promotes long‐term recovery of cerebral blood flow, angiogenesis, and neuronal viability after cerebral ischemia suggest the potential for PTX3 as a promising therapeutic target of clinical relevance." (PMID 33210471, 2021). "PTX3 also promotes sustained long‐term recovery of cerebral blood fluid, angiogenesis, and neuronal viability after cerebral ischemia." (PMID 33210471, 2021). "FGF-7 protein binds to its natural receptor FGFR2β that leads to angiogenesis and PTX3 is a major mediator of angiogenesis and neurogenesis after cerebral ischemia and has a significant impact on the recovery of lateral exercise function." (PMID 34948061, 2021). "The production of PTX3 in brain is dependent on IL-1β release after cerebral ischemia and it mediates the formation of the glial scar and resolution of brain edema." (PMID 31354697, 2019). "Furthermore, absence of PTX3 was associated to marked reduction in poststroke angiogenesis when compared to wild type mice 2 weeks after cerebral ischemia." (PMID 31354697, 2019).
head and neck cancer (5 papers, 2015 to 2024). A primary or metastatic malignant neoplasm affecting the head and neck. "PTX3 can also regulate head and neck cancer cell metastasis by modulating the expression of fibronectin and MMP-9, in which contributes to NF-κB-promoted tumor metastasis." (PMID 27377307, 2016). "Interestingly, we found that EGF significantly induced PTX3 gene expression and protein production in time-dependent manners in head and neck cancer cell lines, but a tiny induction was observed in HeLa cells." (PMID 25797258, 2015). "Other reports suggested that endothelial growth factor (EGF)-induced PTX3 production through the activation of the PI3K/Akt and NF-κB pathways increased MMP-9 and fibronectin expression in head and neck cancer cell metastasis." (PMID 27377307, 2016).
Hepatic steatosis (5 papers, 2008 to 2025). Steatosis is a term used to denote lipid accumulation within hepatocytes. "Further studies are necessary to explain associations between PTX3 production and hormonal dysfunction of adipose tissue as well as liver steatosis and fibrosis." (PMID 32934654, 2020). "Moreover, it has also been shown that, in adolescents, PTX3 levels increased progressively with the severity of the fatty liver." (PMID 32934654, 2020). "However, to fully confirm these hypotheses, imaging studies with an assessment of liver steatosis in magnetic resonance (MR) and PTX3 levels in women with PCOS are necessary." (PMID 32934654, 2020).
Hypercholesterolemia (5 papers, 2014 to 2021). An increased concentration of cholesterol in the blood. "Indeed, measured PTX3 values in both groups are in line with those documented in subjects with cardiovascular risk factors including hypercholesterolemia." (PMID 25014007, 2014). "In patients with hypercholesterolemia, PTX3 correlated with the severity of vascular disease and statin therapy decreased plasma PTX3 levels, which suggests an involvement of PTX3 in vascular inflammation triggered by LDL‐C." (PMID 33210471, 2021). "In patients with hypercholesterolemia, PTX3 correlated with the severity of vascular disease and statin therapy decreased plasma PTX3 levels, suggesting the involvement of PTX3 in the mechanisms by which LDL cholesterol triggers vascular inflammation." (PMID 31998222, 2019). "Higher plasma PTX3 levels were found in familial hypercholesterolemia (FH) patients, and statin treatment again reduced the PTX3 level in these patients." (PMID 31998222, 2019). "In hypercholesterolemia PTX3 correlates with the severity of vascular disease and statin therapy reduces plasma PTX3, suggesting its involvement in the mechanisms by which LDL cholesterol triggers vascular inflammation." (PMID 25014007, 2014).
leukemia (5 papers, 2017 to 2025). A malignant (clonal) hematologic disorder, involving hematopoietic stem cells and characterized by the presence of primitive or atypical myeloid or lymphoid cells in the bone marrow and the blood. "As PTX-3 gene promoter binds to STAT3 which is also activated in leukemia, down-regulation of PTX-3 could stimulate apoptosis of invasive cells." (PMID 36499628, 2022). "Therefore, PTX-3 appears as a reliable marker in monitoring patients with leukemia." (PMID 36499628, 2022). "In other words, PTX-3 inhibition may support patients with leukemia." (PMID 36499628, 2022).
lung adenocarcinoma (5 papers, 2016 to 2024). A carcinoma that arises from the lung and is characterized by the presence of malignant glandular epithelial cells. "Positive expression of MMP-9 is linked with PTX3 expression in lung adenocarcinoma, suggesting an association of PTX3 with tumor grade and severity of malignancies." (PMID 34912809, 2021). "Another study shows that targeting three genes, HGF, PTX3, and S100P, or their associated pathways, could be a promising strategy for inhibiting EMT and combating lung adenocarcinoma (LUAD)." (PMID 39201656, 2024). "On the contrary, knockdown of PTX3 suppresses growth of lung adenocarcinoma A549 and LETPα-2 cells." (PMID 27377307, 2016).
malnutrition (5 papers, 2019 to 2025). Inadequate nutrition resulting from poor diet, malabsorption, or abnormal nutrient distribution. "Considering that PTX3 is expressed in different tissues, including in the adipose tissue, this inflammatory biomarker seems to be more sensitive to inflammation-related malnutrition than CRP, IL-6, and TNF-α in this population." (PMID 31316299, 2019). "On the basis of the unclear results for pentraxin 3, further studies evaluating the role of this protein in cardiac decompensation would be useful, as would exploring the possible association between PXT3 and malnutrition, a condition often associated with HF with a negative influence on prognosis." (PMID 38397422, 2024).
multiple myeloma (5 papers, 2021 to 2022). "In multiple myeloma (MM), PTX3 affects in vitro and in vivo fibroblast growth factor 2-mediated MM angiogenesis, promoting cytotoxicity in MM cells by inhibiting the cross-talk between plasma cells, endothelial cells and fibroblasts." (PMID 36362114, 2022). "In addition to PTX3 protein has been reported to act as an anti-angiogenic factor in multiplemyeloma and to exhibit cytotoxic effects against multiple myeloma cells by impairing signaling between plasma cells bone marrow-derived plasma cells and endothelial cells." (PMID 34048179, 2021).
Myocardial fibrosis (5 papers, 2013 to 2025). "Specifically, echocardiography indicated that PTX3 overexpression promoted tissue remodeling, left ventricular dysfunction, and increased myocardial fibrosis, while these responses were suppressed in ptx3-deficient mice." (PMID 31057548, 2019). "Illustrating the molecular mechanism of PTX3 in myocardial fibrosis provides insights on the transfer of the new mechanistic knowledge on HF pathology into potential biomedical applications." (PMID 35522573, 2022). "Masson staining were conducted to assess the effects of PTX3 KD on myocardial fibrosis in murine HF after MI." (PMID 35522573, 2022). "Here, by bioinformatics analysis and post-MI HF mouse modelling, this study aims to verify the role of PTX3 in myocardial fibrosis and its potential downstream pathway." (PMID 35522573, 2022). "The degree of myocardial fibrosis after TAC was attenuated in PTX3-KO mice than in the respective WT mice (P<0.01)." (PMID 23372656, 2013). "In PTX3-TG mice, the degree of myocardial fibrosis and cardiac fibrosis-related gene expression were markedly higher than in the WT mice." (PMID 23372656, 2013). "Thus, our results suggested that the PTX3 KD decreased the number of cardiac fibroblasts in vivo and also inhibited the activity of cardiac fibroblasts in vitro, suggesting that PTX3 KD attenuates the myocardial fibrosis by inhibiting cardiac fibroblasts." (PMID 35522573, 2022). "However, little is known about PTX3’s molecular mechanism in HF, particularly in myocardial fibrosis." (PMID 35522573, 2022). "Given the evolving role of galectin-3 and pentraxin-3 in cardiovascular pathophysiology—especially their associations with myocardial fibrosis, vascular inflammation, and prognosis in CAD—the lack of serial measurements represents a missed opportunity for a more nuanced analysis." (PMID 40430046, 2025). "PTX3 can counteract the myocardial fibrosis by inhibiting the IL-6/STAT3 pathway, implicating that PTX3 KD may acts as a therapeutic target for HF after MI." (PMID 35522573, 2022).
Opportunistic infection (5 papers, 2021 to 2024). An infection that is caused by a pathogen that would generally not be able to cause an infection in a host with a normal immune system. "Different studies indicate PTX3 as a specific diagnostic and prognostic marker in opportunistic infections, including those caused by S. aureus." (PMID 38668433, 2024). "Among the range of molecules expressed by OB lineage cells besides immune ones, the soluble PRM pentraxin 3 (PTX3) has been recently proposed as a specific and independent diagnostic and prognostic biomarker in opportunistic infections, including those sustained by SA." (PMID 34357987, 2021). "PTX3 genetic variants have been associated to innate resistance to infections in humans and PTX3 is a potential therapeutic target in opportunistic infections." (PMID 34093560, 2021). "Treatment with recombinant PTX3 reduced P. aeruginosa colonization in cystic fibrosis mice and synergized with antifungals in the therapy of A. fumigatus infections, paving the way for the development of PTX3 as potential new therapeutic molecule in these opportunistic infections." (PMID 34093560, 2021). "It is therefore conceivable that the +734A/C SNP (and the others investigated in our association study) determines reduced expression rather than function of the PTX3 protein in vivo, as observed in other opportunistic infections." (PMID 37222419, 2023).
renal failure (5 papers, 2011 to 2024). "First, circulating PTX3 levels and adipose tissue expression of PTX3 mRNA were analyzed and related to measures of body composition in a group of carefully phenotyped incident dialysis patients (CKD stage 5) and non-CKD controls." (PMID 23658833, 2013).
ST Elevation Myocardial Infarction (5 papers, 2015 to 2025). A myocardial infarction that produces elevation in the ST segments of the ECG. "The rs2305619 AA of pentraxin 3 (PTX3), involved in inflammation, was associated with a higher incidence of microvascular obstruction in ST-elevation myocardial infarction patients after primary percutaneous coronary intervention and a higher 30-day mortality." (PMID 39759113, 2025). "Increased PTX3 levels in ST-elevation myocardial infarction (STEMI) patients upon hospital admission have been demonstrated to be independent predictors of 3-month mortality, but not of readmission to hospital for acute heart failure (AHF)." (PMID 25922551, 2015). "We studied the effects of stem cell treatment in ST-elevation myocardial infarction (STEMI) on PTX3 and MPO levels." (PMID 28197227, 2015). "PTX3, IL-6 and hs-CRP were measured at predefined time points, at baseline(before percutaneous coronary intervention (PCI)), at 12 and 72 hours afterPCI in 161 patients with first-time ST elevation myocardial infarction(STEMI)." (PMID 32403934, 2020).